ANKDD1B (ankyrin repeat and death domain containing 1B)
Tractability: No criterion of Open Targets' tractability assessment is met for any kind of drug.
Gene: Protein-coding gene on chromosome 5 (75,611,182 to 75,681,773, forward strand). Ensembl gene ENSG00000189045.
Gene Ontology:
Biological process: signal transduction
Genetic constraint (gnomAD): Loss-of-function variants: 24 observed, 28.76 expected, observed/expected ratio (o/e) 0.83, 90% interval 0.6 to 1.17. The upper end of that interval is the gene's LOEUF score, 1.17, which puts it in group 5 of 6, group 1 being the genes least tolerant of losing a copy. Missense variants: 373 observed, 384.81 expected, observed/expected ratio (o/e) 0.97, 90% interval 0.89 to 1.06. Synonymous variants: 157 observed, 153.72 expected, observed/expected ratio (o/e) 1.02, 90% interval 0.9 to 1.17.
Homologues: Orthologues: chimpanzee ANKDD1B (99% identical), macaque ANKDD1B (95% identical), pig ANKDD1B (82% identical), rat Ankdd1b (76% identical), mouse Ankdd1b (76% identical), rabbit ANKDD1B (65% identical), guinea pig ANKDD1B (51% identical), tropical clawed frog ankdd1b (49% identical), zebrafish ankdd1b (38% identical). Paralogues in human: ANKDD1A (36% identical).
Diseases named in the same sentence as ANKDD1B in open-access papers:
ANKDD1B is named in the same sentence as 12 diseases in open-access papers, as found by Europe PMC text mining. Sharing a sentence is not in itself a finding about the gene and the disease. The quoted sentences say what the papers report.
migraine (9 papers, 2019 to 2025). "ANKDD1B, ankyrin repeat and death domain containing 1B, is linked to the coding of ankyrin-repeat proteins, which are involved in several human diseases, especially migraine and has elevated expression in microglia." (PMID 40634879, 2025). "The study confirmed the association between the ANKDD1B gene and comorbid depression in Chinese migraine patients." (PMID 39144710, 2024). "Another population-based study in China found that ANKDD1B rs34358 was associated with a decreased risk of migraine as a protein-truncating variant." (PMID 39144710, 2024). "In summary, our findings indicate that the ANKDD1B rs904743 variant identified in genome-wide association study was significantly associated with an increased susceptibility to migraine accompanied by depression in Chinese patients." (PMID 39144710, 2024). "While another study suggested a possible association between ANKDD1B and other genes and migraine in people of European ancestry by affecting lipoprotein subfractions." (PMID 39144710, 2024). "The results of the Random Forest algorithm indicated that ANKDD1B rs904743 was a significant risk factor for migraine susceptibility in China." (PMID 39144710, 2024). "The genotype and allele distribution of ANKDD1B rs904743 differed significantly between migraine patients and controls." (PMID 39144710, 2024). "Our study confirmed that ANKDD1B rs904743 may increase susceptibility to migraine with depression in a Chinese population." (PMID 39144710, 2024). "In this study, ANKDD1B rs904743 was associated not only with depression combined with migraine, but also with migraine susceptibility, suggesting that ANKDD1B gene may be a common genetic basis for both disorders." (PMID 39144710, 2024). "For example, the ANKDD1B gene encodes a protein called ankyrin repeat and death domain-containing 1 B. Recent studies have shown that the ANKDD1B gene is involved in vascular and endothelial function and contributes to migraine and blood pressure risk." (PMID 36292730, 2022). "For example, ANKDD1B, a T2D-related gene, is involved in metabolism and inflammation, which may play a role in the pathophysiology of migraine, as previous research reported that inflammatory processes are associated with migraine." (PMID 36292730, 2022). "In assessing the phenotypic and genetic relationship between migraine and lipoprotein subfractions, ANKDD1B was found to be one of the key genes thought to potentially drive migraine." (PMID 38385040, 2024). "In the GWAS study, ANKDD1B and KCNK5 were associated with migraine and MDD etiology as key genes in neural-related signaling pathways and ion channel regulatory pathways." (PMID 39144710, 2024). "ANKDD1B and SERPINA1 were the nearest genes to a genome-wide significant migraine risk SNP, and POC5 was the nearest gene to a genome-wide significant T2D risk SNP." (PMID 36292730, 2022). "After considering broadly defined gene-based evidence for association and accounting for 13,524 gene-based tests, two genes especially stood out as meeting the most stringent statistical criteria for genetic features shared between MDD and migraine, ANKDD1B and KCNK5." (PMID 40634879, 2025). "The study indicates that there is an association between ANKDD1B rs904743 and susceptibility to migraine with and without depression in Chinese patients." (PMID 39144710, 2024). "Although there is little data on ANKDD1B, it may be relevant to the pathophysiology of migraine and T2D due to its role in vascular function." (PMID 36292730, 2022). "Interestingly, some of these loci mapped to genes including ITPK1, ZNF462, RPL30P1, ANKDD1B, THADA, ZNF652, and C20orf203 that have been reported as genome-wide significant in the most recent migraine GWAS." (PMID 36672757, 2022). "The remaining three genes are located at two loci not previously identified for migraine (POC5 and ANKDD1B on chromosome 5q13.3, and TMEM91 on chromosome 19q13.2), thus, representing novel loci for migraine risks." (PMID 32121467, 2020).
ankylosing spondylitis (2 papers, 2018 to 2024). An autoimmune chronic inflammatory disorder characterized by inflammation in the vertebral joints of the spine and sacroiliac joints. "Clinical studies have found that ANKDD1B variants may be associated with ankylosing spondylitis and hypertension." (PMID 39144710, 2024). "In this study, we combined genome-wide linkage analysis and exome sequencing to identify the ANKDD1B gene as a potential locus related ankylosing spondylitis in a Chinese AS pedigree." (PMID 29976160, 2018).
cancer (2 papers, 2021). A tumor composed of atypical neoplastic, often pleomorphic cells that invade other tissues. "Other genes such as VPS13C, ANKDD1B, and MID2 have been rarely investigated in drug resistance‐related cancer research." (PMID 34026427, 2021).
ANKDD1B also shares sentences with these, for which no sentence is quoted: major depressive disorder (3 papers); chronic myeloid leukemia (1); coronary atherosclerosis (1); depression (1); dyslipidemia (1); Hypercholesterolemia (1); Hypertension (1); multiple myeloma (1); ovarian cystadenocarcinoma (1).